ZSCAN4 (zinc finger and SCAN domain containing 4)
Diseases named in the same sentence as ZSCAN4 in open-access papers:
ZSCAN4 is named in the same sentence as 15 diseases in open-access papers, as found by Europe PMC text mining. Sharing a sentence is not in itself a finding about the gene and the disease. The quoted sentences say what the papers report.
head and neck squamous cell carcinoma (5 papers, 2020 to 2024). A squamous cell carcinoma that arises from any of the following anatomic sites: lip and oral cavity, nasal cavity, paranasal sinuses, pharynx, larynx, and salivary glands. "A recent report indicated that the human ZSCAN4 marks and regulates the cancer stem cell (CSCs) phenotype in head-and-neck squamous-cell carcinoma (HNSCC) by altering the epigenetic profile at the promoters of CSCs factors." (PMID 38612707, 2024). "Head and neck squamous cell carcinoma (HNSCC) cancers reactivate ZSCAN4, which in turn regulates the phenotype of cancer stem cells (CSCs)." (PMID 38612707, 2024). "Zscan4, a transcription factor (TF) firstly identified as exclusive of murine 2-cell embryos and murine ESCs (mESCs), is also been associated with stem cell phenotype in human head and neck squamous cell carcinoma (HNSCC)." (PMID 34249759, 2021). "In this study, we investigate the role of Zinc finger and SCAN domain containing 4 (ZSCAN4) in human head and neck squamous cell carcinoma (HNSCC)." (PMID 32507861, 2020). "In the case of cancer cells, ZSCAN4 was recently demonstrated to highly express in human head and neck squamous cell carcinoma and to play important roles in the maintenance of cancer stem cell phenotype, possibly through the enhancement of telomere maintenance." (PMID 35159266, 2022). "We show that ZSCAN4 is transiently expressed in head and neck squamous cell carcinoma (HNSCC) cell lines and is enriched in and marks CSCs." (PMID 32507861, 2020). "Additionally, in head and neck squamous cell carcinoma (HNSCC), ZSCAN4 played an important role in facilitating chromatin remodeling and activating cancer stem cell factor expression, including OCT3/4, NANOG, KLF4, and SOX2." (PMID 36841776, 2023).
breast carcinoma (2 papers, 2018 to 2023). "The expression of ZSCAN4 has been demonstrated in a small proportion of cancer cells, including cervical cancer cells (HeLa), breast cancer cells (MCF7) and osteosarcoma cells (SaOS2 and U2OS)." (PMID 36841776, 2023). "Of note, both the stroma-intensive expression of Zscan4 in the post-treatment patients and significant correlations between Zscan4 and p38/mTOR were validated through pathological assessment of human breast cancer (BCa) patient samples." (PMID 29712904, 2018). "In breast cancer cells (MCF7) and osteosarcoma cells (SaOS2), ZSCAN4 has been found to be directly bound to RAP1 in the nucleus, possibly regulating shelterin complex-controlled telomere elongation in both telomerase positive and alternative lengthening of telomere pathways." (PMID 36841776, 2023).
Edwards syndrome (1 paper, 2015). "To see whether ZSCAN4 can function comparably on other trisomic aneuploidies, we treated non-immortalized primary fibroblast cells (AG12614: 47,XX,+18) derived from an individual with trisomy 18—Edwards syndrome." (PMID 26324424, 2015).
embryonic carcinoma (1 paper, 2017). "To define the role of extruded syntaxin-4 in ES cell behavior, we used the simpler, stable embryonic carcinoma (EC) F9 stem cell system, in which ES cell–specific regulators of differentiation, including a set of Zscan4 proteins, are undetectable." (PMID 28057922, 2017). "Embryonic carcinoma cell lines F9 and P19CL6, which maintain undifferentiated states independently of Zscan4 proteins, exhibited similar cellular behaviors upon stimulation with cell surface syntaxin-4." (PMID 28057922, 2017).
facioscapulohumeral muscular dystrophy (1 paper, 2025). An autosomal dominant disorder affecting the skeletal muscles of the face, scapula, and upper arm. "Aberrations in Zscan4, which are implicated in facioscapulohumeral muscular dystrophy (FSHD) 1 and 2 - a disease characterized by progressive muscle weakness and atrophy - arise in part from dysfunctions at the neuromuscular junction (NMJ)." (PMID 41033462, 2025). "Aberrations in Zscan4 have been linked to Facioscapulohumeral Muscular Dystrophy (FSHD) and we observed an increase in Zscan4 mRNA levels in OGT-CDG mESCs." (PMID 41033462, 2025).
microcephaly (1 paper, 2025). A congenital or acquired developmental disorder in which the circumference of the head is smaller than normal for the person's age and sex. "In summary, our findings suggest that OGT-CDG mutations result in dysregulation of the Ogt-Tet complex, which in turn alters the transcriptional profiles of genes critical for development, including Zscan4 and several candidates linked to ID and microcephaly." (PMID 41033462, 2025).
squamous cell carcinoma (1 paper, 2024). A carcinoma arising from squamous epithelial cells. "We have previously shown that ZSCAN4 is transiently expressed in human squamous cell carcinoma cells and increases the frequency of cancer stem cells." (PMID 38612707, 2024).
urothelial carcinoma (1 paper, 2023). A malignant neoplasm derived from the transitional epithelium of the urinary tract (urinary bladder, ureter, urethra, or renal pelvis). "Low expression of ZSCAN4 predicted worse outcome in urothelial carcinoma and might have potential regulatory role in cell mitosis." (PMID 36841776, 2023).
cancer (14 papers, 2015 to 2025). A tumor composed of atypical neoplastic, often pleomorphic cells that invade other tissues. "These authors analyzed two cell lines, MCF7 and SaOS2, epithelial/telomerase+ and mesenchymal/telomerase−, respectively, and found that Zscan4 was present in cancer cells from both cell lines." (PMID 41303422, 2025). "Transfection of cancer cells with Rap1 siRNA resulted in significantly reduced expression of Zscan4, whereas overexpression of Rap1 gave rise to greater Zscan4 expression." (PMID 41303422, 2025). "In these cancers, ZSCAN4 activation enhances cell cycle processes and prevents replicative senescence, thereby promoting tumor growth and metastasis." (PMID 40427614, 2025). "In cancers such as sarcoma and lymphoma, where DUX4 is re-expressed due to genetic rearrangements or mutations, ZSCAN4 expression results in telomere repair." (PMID 40427614, 2025). "As a target gene of DUX4, ZSCAN4, which is essential for telomere extension in embryonic stem cells, is also activated in numerous cancers that express DUX4, potentially enhancing tumor replicative capacity." (PMID 40427614, 2025). "Understanding the mechanism by which ZSCAN4 affects telomere chromatin remodeling is important for the development of future therapeutic approaches targeting the replicative lifespan of cancer stem cells." (PMID 38612707, 2024). "Our study reveals a novel role for human ZSCAN4 in facilitating histone H3 acetylation at the telomeres and demonstrates its importance for telomere maintenance in cancer cells." (PMID 38612707, 2024). "We recently reported that the human ZSCAN4 marks and regulates the cancer stem cell (CSCs) phenotype in head-and-neck squamous-cell carcinoma (HNSCC) by altering the epigenetic profile at the promoters of CSC factors." (PMID 38612707, 2024). "Understanding how ZSCAN4 modulates the telomeric chromatin is crucial for developing new therapeutic approaches to target cancer stem-cell replicative lifespan." (PMID 38612707, 2024). "This study demonstrates for the first time a novel role of human ZSCAN4 in promoting histone H3 acetylation at the telomere chromatin and its significant contribution to telomere maintenance in cancer stem cells." (PMID 38612707, 2024). "We recently reported that the human ZSCAN4 is also transiently expressed, thereby increasing the frequency of cancer stem cells, in HNSCC." (PMID 38612707, 2024). "In this study, we show for the first time a novel role of human ZSCAN4 in facilitating histone H3 acetylation at the telomere chromatin and determine its significant contribution to telomere maintenance in cancer stem cells." (PMID 38612707, 2024). "Though the role of ZSCAN4 in embryonic stem cells became increasingly clear in recent years, little is known with respect to the biological function of ZSCAN4 in cancer cells." (PMID 36841776, 2023). "This was the first study that investigates the prognostic significance of ZSCAN4 in a well-defined cohort of cancer patients." (PMID 36841776, 2023). "In human ALT cancer cells, ZSCAN4 is highly expressed, and its expression is critical for extending these short telomeres." (PMID 37569497, 2023). "In human head and neck squamous cell carcinoma, depletion of ZSCAN4 downregulates the expression of cancer stem cell (CSC) markers, severely affecting tumorsphere formation and tumor growth." (PMID 37569497, 2023). "Overall, our studies suggest ZSCAN4 plays a critical role in the maintenance of HNSCC cancer stem cells." (PMID 32507861, 2020). "To determine if expression of human ZSCAN4 leads to similar epigenetic changes in cancer cells, we examined a panel of acetylation patterns of Histone 3 Lysine residues 9, 14, 18, and 27 (H3K9ac, H3K14ac, H3K18ac, and H3K27ac) after ZSCAN4 induction." (PMID 32507861, 2020). "Much like other embryonic factors, the human ZSCAN4 has been proposed to have significance in cancer." (PMID 32507861, 2020).
cancer (continued). "To assess the potential of ZSCAN4 as a therapeutic target in cancer, we assessed the impact of ZSCAN4 depletion on tumor growth in vivo using the NSG mouse xenograft model." (PMID 32507861, 2020). "Overall, our findings suggest that ZSCAN4 marks, promotes, and maintains the most highly tumorigenic population of cancer cells." (PMID 32507861, 2020). "Interestingly, it was reported that ZSCAN4 was subjected to ubiquitination-dependent degradation in a human cancer cell line Tu167 by an E3 ubiquitin ligase RNF2055." (PMID 40750602, 2025). "Specifically, ZSCAN4 is known for its role in maintaining telomeres and responding to DNA damage by regulating telomere lengthening and chromatin remodeling, thereby increasing the replication potential of cancer cells." (PMID 40427614, 2025). "Targeting ZSCAN4 may offer new therapeutic approaches to effectively limit or enhance the replicative lifespan of stem cells and cancer cells." (PMID 38612707, 2024). "Our research suggests ZSCAN4 may represent a new link between telomere maintenance and the cancer stem cell phenotype." (PMID 38612707, 2024). "Interestingly, in these two types of cancer cells, the protein expression of ZSCAN4 was also dependent on RAP1." (PMID 36841776, 2023). "ZSCAN4 governs chromatin remodeling in human cancer stem cells." (PMID 36306355, 2022). "Our data indicate that ZSCAN4 might be a useful target to complement cancer therapy using telomerase inhibitors." (PMID 35159266, 2022). "Here, we show that reduced repressive epigenetic modifications at Zscan4 promoters de-repress Zscan4, which contributes to telomere maintenance in both late generation Terc-/- ES cells and telomerase-deficient human ALT-U2 OS cancer cells." (PMID 35159266, 2022). "In this research, we studied the role of human ZSCAN4 in cancer." (PMID 32507861, 2020). "Blocking ZSCAN4 alone, or in conjunction with additional chemotherapeutic drugs, may offer a new approach for cancer treatment with a wider therapeutic window and means to restore cancer replicative aging in novel therapeutics." (PMID 38612707, 2024). "Accordingly, in terms of the known biological function of telomere elongation of ZSCAN4, ZSCAN4 expression in cancer cells may aid in telomere elongation, prevent cellular senescence and maintain normal karyotype for many cell divisions, and which, subsequently, result in cell immortalization." (PMID 36841776, 2023). "Given the similarity of telomerase-deficient mESCs and ALT human cancer cells in maintaining telomeres independent of telomerase involvement for cellular proliferation, we hypothesized that ZSCAN4 may also be involved in telomere maintenance of human ALT U2 OS cancer cells." (PMID 35159266, 2022). "However, it remained unclear whether the human ZSCAN4 is involved in cancer, or if it drives or marks cells with open chromatin states." (PMID 32507861, 2020). "Like ZSCAN4, embryonic factors OCT3/4, SOX2, and NANOG are reactivated in cancer and have further been classified as CSC markers that regulate self-renewal and contribute to tumor aggressiveness and metastasis." (PMID 32507861, 2020). "More recently, a zinc finger transcription factor, named Zscan4 (Zinc Finger and Scan Domain Containing 4), was found to be essential for SASP development in human stromal cells exposed to acute stress upon anti-cancer treatments." (PMID 33371508, 2020). "The prominent concordance between distinct Zscan4 expression and key SASP regulator activation observed in cancer patient specimens prompted us to further explore the functional implication of Zscan4 in damaged stromal cells." (PMID 29712904, 2018). "The expression of ZSCAN4 is not detectable in normal adult differentiated cells, making it an attractive target for cancer therapy." (PMID 38612707, 2024). "Although the human ZSCAN4 is not expressed in adult differentiated cells, it is re-expressed in various types of cancer." (PMID 38612707, 2024).
cancer (continued). "While the human ZSCAN4 is not expressed in adult differentiated cells, it is re-expressed in various types of cancer." (PMID 38612707, 2024). "The functions of ZSCAN4 are not specifically related to muscle, but rather to the epigenetic regulation of pluripotency in normal and cancer stem cells, affecting their growth." (PMID 39009887, 2024). "However, the exact mechanisms on how Zscan4 facilitates telomere elongation in both mouse ESCs and human ALT-U2 OS cancer cells remain to be elucidated." (PMID 35159266, 2022). "Further, Zscan4 expression appeared more readily inducible by DT agents in stromal cells rather than cancer epithelial cells of the same organ of origin, the prostate, suggesting a cell lineage dependency." (PMID 29712904, 2018). "The functional role and prognostic significance of ZSCAN4 in cancer have never been elucidated." (PMID 36841776, 2023). "Moreover, knockdown and Knockout of human ZSCAN4 in U2 OS cells significantly shortened telomere length, suggesting human ZSCAN4 also functions in the contribution of telomere maintenance in human ALT cancer cells without telomerase activity." (PMID 35159266, 2022). "Zscan4 is only expressed in two-cell embryos and a small proportion of embryonic stem cells at a given time, suggesting that it may not be the target for TRIM28 to regulate the ALT pathway in cancer cells." (PMID 34330324, 2021).
tumor (7 papers, 2015 to 2025). "The analytic data suggested that Zinc finger and SCAN domain containing 4 (ZSCAN4) was found to be significantly associated with tumor invasion depth, characterized by significant downregulation in muscle-invasive UBUCs (T2–T4) when compared with non-muscle-invasive UBUCs (Ta-T1)." (PMID 36841776, 2023). "Typically, telomere shortening restricts cell division, but ZSCAN4 reactivation helps overcome these limitations and promotes tumor cell longevity and continuous division." (PMID 40427614, 2025). "In line with the finding from our initial expression profiling analysis of UBUC transcriptome (GSE31684), ZSCAN4 was identified as a tumor suppressor in UC." (PMID 36841776, 2023). "We pathologically analyzed p38 and mTOR activation via a similar appraisal strategy in a case-to-case manner, and found synchronized changes in Zscan4 expression and p38/mTOR activation in the tumour stroma of NSCLC patients." (PMID 29712904, 2018). "Subsequently, DUX4 activates a shared set of genes, including ZSCAN4, TRIM, PRAMEF, and retrotransposon-associated elements, which are expressed in both early embryos and tumor cells, thereby inducing a metastable, totipotent-like state and enhancing immune evasion and cellular plasticity." (PMID 40427614, 2025). "Depletion of ZSCAN4 was found to have inhibitory effect on tumor growth in HNSCC." (PMID 36841776, 2023). "In this study, we firstly identified that ZSCAN4 acts as a tumor suppressor in UC." (PMID 36841776, 2023). "However, more studies are needed to clarify mechanisms about the tumor suppressor role of ZSCAN4 in UC." (PMID 36841776, 2023). "Moreover, ZSCAN4 depletion results in reduced ability to form spheroids in vitro and severely affects xenograft tumor growth in vivo." (PMID 32507861, 2020). "Importantly, our data indicate that ZSCAN4 depletion results in a significant inhibition of more than 98% in tumor growth and only half of the mice present with a palpable tumor after 9 weeks." (PMID 32507861, 2020). "In contrast, depletion of ZSCAN4 results in the downregulation of CSC markers, reduced ability to form tumorspheres, and a limitation in tumor growth." (PMID 38067304, 2023). "This highlights the importance of ZSCAN4 in maintaining the CSC phenotype and driving tumor progression in HNSCC." (PMID 38067304, 2023). "Consistently, ZSCAN4 depletion leads to downregulation of CSC markers, decreased ability to form tumorspheres and severely affects tumor growth." (PMID 32507861, 2020). "Upon separation of epithelium and stroma from tumour tissues by laser capture microdissection (LCM), we observed considerably increased Zscan4 transcript in the stroma of post-treated patients." (PMID 29712904, 2018).
infection (2 papers, 2023 to 2025). The state of being infected such as from the introduction of a foreign agent such as serum, vaccine, antigenic substance or organism. "Western Blot as well as qRT-PCR experiments further confirmed the expression of DUX4 and known DUX4-target genes TRIM48, TRIM49, ZSCAN4, ZSCAN5a, ZSCAN5d and RFPL4A upon HSV-1, HCMV and KSHV-infection 25 in different experimental settings." (PMID 38168299, 2023).
ZSCAN4 also shares sentences with these, for which no sentence is quoted: cervical cancer (1 paper); leukemia (1); osteosarcoma (1); urinary bladder urothelial carcinoma (1).